CSF1R (colony stimulating factor 1 receptor)
Diseases named in the same sentence as CSF1R in open-access papers (continued):
Sharing a sentence is not in itself a finding about the gene and the disease.
cancer (continued). "Delineate structure-based inhibition of colony-stimulating factor-1 receptor (CSF1R) by small molecule CSF1R inhibitors in clinical development for target identification and potential lead optimization in cancer therapeutics since CSF1R is a novel predictive biomarker for immunotherapy in cancer." (PMID 37711590, 2023). "Image registration matching between RNAscope spots and stLearn’s predicted CCI events (IL34 and CSF1R) indeed showed consistent correspondence between the predicted and observed interaction events, mostly at the border between cancer nests and normal tissue areas." (PMID 38007580, 2023). "MiR-21 regulates colony-stimulating factor 1 receptor (CSF-1R) for macrophage repolarization, whereas a double feedback loop regulated by miRNA-23a/27a/24-2 effectively regulates macrophage polarization and regulates cancer progression." (PMID 35886037, 2022). "Macrophage colony-stimulating factor 1 (CSF1) secreted by cancer cells binds to its receptor (CSF1R) on the macrophage membrane, and in turn, activates the downstream signaling pathway responsible for the polarization of TAMs to the immunosuppressive phenotype." (PMID 35216342, 2022). "This suggests downstream CSF-1R signaling may vary between macrophage subsets, which can have implications towards CSF-1R blockade therapies targeting macrophages in cancer." (PMID 35821822, 2022). "Because TAMs are highly heterogeneous depending on the cancer type, whether CSF1R inhibition can benefit a broad range of patients with cancer remains unknown." (PMID 36248881, 2022). "Besides to regulate TAMs, accumulating evidence suggest that IL-34 stimulates cancer cell proliferation through its ability to interact with CSF1R in cancer cells." (PMID 36359228, 2022). "In contrast, F4/80high TAMs had relatively lower CSF-1R expression both surface and intracellularly, which may impact their response to CSF-1R blockade therapies in cancer." (PMID 35821822, 2022). "In addition, we demonstrate that the simultaneous inhibition of Axl, Mer, and CSF1R induces antitumor effects by altering the immune profile and cancer cell phenotype in the TME." (PMID 36230744, 2022). "Considering the complex relationship between CSF1/CSF-1R-expressing carcinoma cells and macrophages, synthesis of OPN is of particular interest since OPN is a chemoattractant for macrophage and regulates its adhesion, migration, differentiation, and production of cytokine." (PMID 36555673, 2022). "Moreover, it was demonstrated that inhibition of CSF-1R can improve the prognosis of cancer patients." (PMID 34178692, 2021). "Collectively, blockade of the CSF-1/CSF-1R axis may be a potential strategy in cancer therapy, especially for TGCTs." (PMID 34178692, 2021). "Therefore, blocking CSF‐1/CSF‐1R activation is becoming an important therapeutic strategy to inhibit cancer growth and metastasis." (PMID 33463063, 2021). "Therefore, artificial overexpression of CXCL12 can rescue cancer cells in docetaxel and pexidartinib, which would otherwise be killed by CSF-1R inhibition." (PMID 34069563, 2021). "Indeed, pharmacological CSF1R inhibition is under investigation as a therapeutic strategy for cancer therapy application." (PMID 34298983, 2021). "CSF1R, a receptor for colony stimulating factor 1, is overexpressed in many cancers." (PMID 34487971, 2021). "Thus, blocking CSF-1 and CSF-1R-mediated signaling can be a promising strategy for cancer immunotherapy." (PMID 34178692, 2021). "Whether combined assessment of CSF-1R expression on both the carcinoma cells and immune cells demonstrates better predictive capacity needs further investigation in correlative studies linked to trials of CSF-1R-targeted therapies." (PMID 34830923, 2021). "In addition, TAMs overexpressing CSF1R correlate with poor prognosis and poor overall survival in several human cancers." (PMID 31809612, 2020).
cancer (continued). "In turn, cancer cells express colony stimulating factor 1 (CSF-1), also known as macrophage stimulation factor-1 (M-CSF), a powerful chemotactic molecule for TAMs, which express the colony stimulating factor 1 receptor (CSF1R)." (PMID 32867288, 2020). "Therefore, targeting macrophages, such as anti-CSF1R antibodies, have emerged as attractive therapeutic approaches in various types of cancer." (PMID 33123478, 2020). "Furthermore, high-impact breakthroughs in the field of CSF1R inhibitors have identified the mechanisms by which CSF1R-expressing cells can promote the growth of cancer cells." (PMID 32801364, 2020). "However, the use of CSF1R inhibitors alone as a cancer treatment has also drawn conflicting conclusions." (PMID 32801364, 2020). "Recent examples of kinase inhibitors targeting cancer-associated immune cells include small molecule inhibitors directed towards Bruton’s tyrosine kinase (BTK), colony-stimulating factor-1 receptor (CSF-1R), and PI3Kgamma." (PMID 31817861, 2019). "A number of CSF1R inhibitors are currently under evaluation in the clinic for cancer therapy." (PMID 31753024, 2019). "Depending on the cancer type, blockade of CSF-1R signaling showed variable outcomes." (PMID 31611871, 2019). "Attempts to eliminate TAMs using mAbs against colony stimulating factor 1 (CSF-1) or small molecule inhibitors targeting the c-fms tyrosine kinase of its receptor (CSF-1R/CD115) have proven effective in various murine cancer models and are investigated in numerous clinical trials." (PMID 30938231, 2019). "In parallel, 3D185 could potently inhibit the proliferation of CSF-1/CSF-1R-dependent cancer cell lines and the survival of CSF-1-induced M2-like ‘protumor’ macrophages." (PMID 31438996, 2019). "Spatial profiling of TAM iron deposit infiltration defined regions of maximal accumulation and response to the CSF1R inhibitor, and revealed differences between microenvironments of human cancer according to levels of polarized macrophage iron accumulation in stromal margins." (PMID 30696910, 2019). "Many CSF1R inhibitors, including some that are kinase-specific, can be found in both academic and patent literature, and several have proceeded to clinical trials for the treatment of RA and various types of cancer." (PMID 30551596, 2018). "Blockade of CSF1R has been shown to improve chemotherapy‐induced antitumor immunity in mouse cancer models leading to the hypothesis that targeting the CSF1R/CSF1 interaction in combination with immune checkpoint blockade could have a synergistic response." (PMID 30003190, 2018). "CSF1R also provides critical autocrine signals that promote cancer cell survival and proliferation." (PMID 29323162, 2018). "However, several reports have showed that CSF1R expression can be also detected in other cells such as endothelial cells and importantly in cancer cell lines and primary cancer tissues." (PMID 29323162, 2018). "In this regard, the observed differences in the IL-34/CSF-1R ratio may play a role in both, myeloid and cancer cells." (PMID 29796177, 2018). "Moreover, intracellular CSF-1R signaling not only regulates cancer cell survival and migration, but also stimulates CSF-1/CSF-1R, indicating that the expression of CSF-1 and CSF-1R is influenced by an autocrine loop." (PMID 29228668, 2017). "CSF-1R and CSF-1 are modulated by the autocrine system contributing to aggressive cancers." (PMID 29228668, 2017). "This review focuses on motility signals transduced by the CSF-1R upon activation by CSF-1, and how these signals might be targeted to treat disease, particularly cancer." (PMID 28629162, 2017). "High expression of CSF-1R indicates a poor cancer prognosis." (PMID 29228668, 2017). "Validated miR-155 target genes are present in multiple pathways associated with cancer and cancer progression, including EMT (SMAD5), proliferation (SOCS1, INPP5D, and CSF1R), block of differentiation (SPI1, CEBPB), and apoptosis (CASP3, FADD, APAF1, and FOXO3A)." (PMID 27128908, 2016).
cancer (continued). "However, the exact role of the various ligands/receptor interactions of CSF1R pathway in cancer remains to be clarified." (PMID 26066800, 2015). "CSF1R inhibitors are currently being tested in clinical trials of cancer therapy in patients." (PMID 26635798, 2015). "CSF-1R signalling is relevant both for macrophages and cancer cells." (PMID 26174804, 2015). "Interestingly, we showed that their co-culture leads to up-regulation of CSF in macrophages and up-regulation of CSFs and CSF-1R in cancer cells." (PMID 23561040, 2013). "In fact, several anti-cancer drugs target MCSF1R (macrophage colony-stimulating factor 1 receptor), MSCGFR (mast/stem cell growth factor receptor), POTPKABL1 (proto-oncogene tyrosine-protein kinase ABL1) and VEGFR2 (vascular endothelial growth factor receptor 2), among others." (PMID 22768266, 2012). "Given the diminished CSF1R transcript levels in SPP1hi-TAMs, this could partly explain the clinical ineffectiveness of CSF1R antagonism in human patients with cancer compared with pre-clinical models." (PMID 39633050, 2025). "However, few data are currently available on the efficacy of anti-CSF-1R drugs in cancer." (PMID 38254773, 2024). "Thus, understanding the molecular mechanisms governing CSF-1R expression and function in cancer cells, and whether these mechanisms mirror those in immune cells, is fundamental for developing new CSF-1R-targeted cancer therapies." (PMID 39457693, 2024). "However, a phase 1b study (NCT02323191) assessed the anti-cancer activity, safety, pharmacodynamics, and pharmacokinetics of the anti-CSF1R monoclonal antibody emactuzumab in combination with atezolizumab in patients with advanced cancer who received immunotherapy." (PMID 38022518, 2023). "In addition, the combination of anti-CD40 and anti-CSF-1R not only promotes the maturation and differentiation of inflammatory macrophages and DCs but also drives the effective initiation of effector T cells during cancer immunotherapy." (PMID 36739406, 2023). "Moreover, it is not a substrate of the P-glycoprotein efflux pump as it strongly binds with Cys666 which is a residue of the ATP binding site, thus evading one of the most significant drug resistance mechanisms, making it a promising drug candidate against cancers overexpressing CSF1R." (PMID 37711590, 2023). "(±)-KU has an anti-cancer effect and could bind with CSF1R and AKR1B1." (PMID 37959760, 2023). "CSF1R, the cellular receptor for Colony Stimulating Factor-1 (CSF1) and Interleukin 34 (IL-34), occupies a central role in manipulating the behavior of TAMs, and the dysregulation of CSF1R signaling has been implicated in cancer progression and immunosuppression in many specific cancers." (PMID 36983741, 2023). "The CSF1 receptor (CSF1R) regulates multiple aspects of macrophage function as well as survival, proliferation and differentiation from monocyte precursors and CSF1R inhibition has been shown to suppress tumourigenesis and reduce resistance to chemotherapy in other cancer models." (PMID 37441092, 2023). "Therefore, the development of kinase inhibitors targeting CSF1R could be an effective cancer treatment strategy." (PMID 36770611, 2023). "Targeting carcinogen-regulated immune factors like M-CSF/CSF1R in combination with ICB therapy highlight promising therapeutic strategies that can be uncovered by exploring the TMB/neoantigen-independent immunological impacts of environmental carcinogens on cancer development." (PMID 37843274, 2023). "CSF-1R expression in these cells were altered with age, which may impact the migration, expansion, differentiation, and survival of TAMs and, therefore, may contribute to cancer progression." (PMID 35821822, 2022). "Therefore, inflammaging could impact monocyte/macrophage differentiation and CSF-1R expression during aging and cancer." (PMID 35821822, 2022).
cancer (continued). "We then checked the expression of the canonical cell-type markers: cancer/epithelial cell marker genes (Cdh1, Krt18, and Krt5); mesenchymal cell marker genes (Col1a1, Col1a2, and Col3a1); immune cell marker genes (Ptprc, Cd68, and Csf1r); and endothelial cell marker genes (Pecam1, Emcn, and Cdh5)." (PMID 34497807, 2021). "However, the expression of CSF-1R+ macrophages did not reveal any significant prognostic associations in either the training or validation sets of the BC Cancer series (HR 1.0, 95% CI 0.80–1.27; p = 0.97)." (PMID 34830923, 2021). "Strengths of our study include the utilization of a hypothesis-driven training–validation approach for evaluation of CSF-1R expression and the large size of the BC Cancer cohort, for there exist previously generated extensive data relevant to immune biomarkers." (PMID 34830923, 2021). "CSF1R-expressing cells may play an anti-inflammatory role or a cancer-suppressive role." (PMID 32801364, 2020). "Thus, CSF1R inhibition strategies may serve dual potentials in killing cancer and protecting the normal tissue function." (PMID 31753024, 2019). "However, it is still unclear whether inhibition of CSF-1R similarly affects monocyte-derived and tissue-resident macrophage subsets in different cancer types, which needs to be addressed to fully capture either the efficacy or failures of such treatments." (PMID 31611871, 2019). "Hence, TSC-22 inhibits cancer cell proliferation induced by CSF-1R." (PMID 29228668, 2017). "CSF-1R expressed by cancer cells does not have any mutations compared to the native receptor (data not shown), indicating that it must depend on either autocrine or paracrine signalling to support cancer expansion." (PMID 26174804, 2015). "Notably, the CSF1/CSF1R signaling axis is overexpressed in several epithelial cancers, and there is clinical evidence that this pathway plays a role in radio-resistance of some cancers." (PMID 24019961, 2013). "Radioresistance arises from cancer stem cell maintenance (CD133/HMGB2), TAM polarization (CSF-1R/CD44), and enhanced homologous recombination (RAD51)." (PMID 42125691, 2026). "The levels of CSF1, the other ligand of CSF1R, remained unchanged in IL34-OE cancer cells, indicating that the increase in MD-TAMs was a direct consequence of an IL34-enriched TME." (PMID 40538439, 2025). "While CSF1R inhibitors excel in CSF1R-dependent tumors like TGCT, most cancers require multimodal strategies to overcome resistance." (PMID 40422244, 2025). "In this review, we conducted an in-depth analysis of CSF-1R expression across these various cell types in the TME and highlighted the significant implications for cancer progression." (PMID 39457693, 2024). "CSF-1R inhibitors like PLX3397 and RG7155 offer several advantages and disadvantages in cancer treatment." (PMID 39286635, 2024). "The Colony stimulating factor-1 receptor (CSF1R or FMS) is RTK class III which strongly correlates with oncogenesis and poor prognosis of many types of cancer, including breast carcinomas." (PMID 38822100, 2024). "Immunohistochemical imagines of cancer and paracancer shows AMIGO2 and CSF1R are up-regulated on PDAC tissue compare to paracancer tissue." (PMID 38189855, 2024). "For instance, GSTO2 and PGF were down-regulated while CSF1R, DDB2, HMOX1 and PGFB were up-regulated in both cancers." (PMID 38790250, 2024). "The correlation analysis of 24 immunosuppressants indicated that EDNRA was positively correlated with ADORA2A, CSF1R, KDR, TGFB1, and TGFBR1 in cancers, including BLCA, CHOL, ESCA, READ, and STAD." (PMID 39601333, 2024). "According to in silico molecular docking studies and in vitro si-RNA studies, trans-(−)-kusunokinin targeted CSF1R, inhibiting the receptor and AKT signalling cascade, and thus suppressing cancer cell proliferation and metastasis." (PMID 38822100, 2024).
cancer (continued). "CSF1R activation also triggers the STAT1/3/5 pathways, which regulates several target oncogenes and affects cancer progression, proliferation, anti-apoptosis, metastasis, as well as chemoresistance and survival activities." (PMID 38822100, 2024). "We also noted that anti-CD47 when combined with olaparib downregulated immunosuppressive myeloid markers in cancer cells specifically, TGFBR1 and CSF1R, which has been shown to correlate with therapy resistance." (PMID 37468567, 2023). "Sunitinib inhibits PDGFRs, VEGFRs, c-kit, FLT3, CSF-1R and RET and is FDA approved for the treatment of several cancers." (PMID 35629326, 2022). "TAMs are polarized to the M2 phenotype upon the interaction between its colony-stimulating factor 1 receptor (CSF1R) and the macrophage colony-stimulating factor 1 (MCSF) produced by cancer cells." (PMID 35335881, 2022). "Many targets, including PDGFR, CD44, CSF1R and NTRK2, have small-molecule inhibitors approved for clinical use or are currently under clinical trials for cancer treatment, including glioblastoma." (PMID 36216799, 2022). "In this analysis, high-grade cancer regions with higher expression of NOS3 had elevated CSF1, CSF1R, and CD206." (PMID 36209194, 2022). "Compared with HD, PB of BC was markedly increased in CSF1R+ BMBP, as we described in mice with cancer." (PMID 36104343, 2022). "In this study, we firstly found that CSF-1R was largely up-regulated in COAD tissues, compared with para-carcinoma tissue." (PMID 35444953, 2022). "Blocking CSF1R results in remarkably reduced TAMs, enhanced antitumor T cell responses, and enhanced efficacy of ICI for the treatment of several cancer types." (PMID 34141607, 2021). "Because both analyses showed that OLFML2B was positively correlated with macrophage content, we input cancer-related macrophage markers into the web tool “CellMarker” and obtained experimentally verified markers: CD14, CD68, CD163, CSF1R, ITGAM, and MRC1." (PMID 34868901, 2021). "Since IL-2 had been applied in cancer immunotherapy clinically, it is worth testing the utility of IL-2 in CRC patients with CSF1R c.1085 genotype A_A." (PMID 34830445, 2021). "Pan-cancer immune profiling suggested that the selected HT parameters elevated the expression of chemo-attractants (CCL8 and CSF1R) and cell adhesion molecules (ICAM and VCAM)." (PMID 33391491, 2021). "Considering the top drugs able to modulate the predicted candidate genes, both Dasatinib and Ilorasertib share the same target genes (LYN, CSF1R, FYN) and are used as anti-cancer drugs." (PMID 33918694, 2021). "For instance, G-Rh2 induces the apoptosis of cancer cells by inhibiting FGFR2, CSF1R, EGFR, and LYN." (PMID 33488754, 2020). "In the “pathways in cancer”, PIK3R5, SPI1, and CSF1R are most relevant to FPR3 expression (Figures 7A1–A3)." (PMID 33679387, 2020). "Colony-stimulating factor 1 receptor (CSF-1R) is an important receptor for MDSC migration, and its inhibitor BLZ945 and anti-PD-1 combined with anti-PD-L1 can effectively cure cancer." (PMID 32325683, 2020). "Provided the additional supportive background, the fact that CSF1R and DAPK1 were found to correlate with cancer diseases promoted these compounds as potential antiproliferative molecules." (PMID 31809612, 2020). "To evaluate 3D185’ potential advantage of dual targeting FGFR and CSF1R with equal potency, we further used a co-cultured context with FGFR3-driven RT112 cancer cell line and CSF-1-differentiated human macrophages." (PMID 31438996, 2019). "This further supports the observed antagonistic effect of CSF1R and AURKB, where the inhibition of both rescued the cancer cells." (PMID 31312514, 2019).